INS (insulin)
Diseases named in the same sentence as INS in open-access papers (continued):
Sharing a sentence is not in itself a finding about the gene and the disease.
Cognitive impairment (continued). "Increased adipose tissues have been reported to increase secretion of proinflammatory cytokines and impair insulin sensitivity, in which both conditions were associated with cognitive impairment among older adults." (PMID 34437646, 2021). "The decline in insulin signaling is known to be linked to both cognitive impairment and liver diseases." (PMID 34955810, 2021). "Glucose homeostasis and insulin regulation is increasingly being recognized as a risk factor for cognitive impairment." (PMID 31973065, 2020). "Long-term fructose-drinking (16 weeks) caused neuroinflammation associated with impaired insulin signaling, oxidative stress, reduced activity of the cholinergic system and cognitive impairment in both the hippocampi and the cerebral cortices of rats." (PMID 33374894, 2020). "For example, HFD feeding in another AD mouse model (APP23 mice) caused cognitive deficits and increased hippocampal and cortical Aβ deposition and insulin resistance was reported to increase hyperphosphorylation of Tau via GSK-3β activity." (PMID 33003412, 2020). "HFD-induced disruption of the brain’s insulin signaling has been reported to increase the risk of developing cognitive impairment and dementia." (PMID 31963819, 2020). "Cognitive impairment following HFD consumption is associated with neuroinflammation impairing insulin signaling in the hippocampus of experimental animals." (PMID 30761088, 2019). "Impaired insulin signal transduction and tau hyperphosphorylation in whole brain homogenates have been associated with cognitive deficits in mice (9 weeks post-STZ)." (PMID 31451429, 2019). "At least three studies using post-mortem brains have suggested that AD (or cognitive impairment) is associated with impaired insulin signaling." (PMID 29945658, 2018). "Of interest, intranasal insulin delivery to CRS mice restored impaired insulin signaling and rescued hippocampal cognitive deficits, indicating that dysregulated insulin signaling underlies defective hippocampal function following psychological stress." (PMID 29970188, 2018). "To investigate the possible underlying mechanisms by which insulin prevents the cognitive impairment of ICV-STZ rats, we evaluated the levels of pre- and post-synaptic proteins among these three groups." (PMID 28382978, 2017). "The underlying molecular mechanism by which intranasal insulin prevents anesthesia-induced cognitive impairment remains to be elucidated." (PMID 26879001, 2016). "Although two studies have shown that cognitive impairment was associated with elevated plasma insulin level two hours post glucose loading (oral glucose tolerance test), we did not see an association between fasting serum insulin and MMSE score." (PMID 27642517, 2016). "In the cross-sectional analysis at baseline, higher levels of IGF-1 and insulin were associated with lower cognitive scores and thus with a higher degree of cognitive impairment." (PMID 27627435, 2016). "Our results indicated that chronic APN deficiency inactivated AMPK causing insulin desensitization and elicited AD-like pathogenesis in aged mice which also developed significant cognitive impairments and psychiatric symptoms." (PMID 27884163, 2016). "Cognitive impairment is present in AD, T1D (due to insulin deficiency) and T2D (due to impaired insulin sensitivity of the brain)." (PMID 27240327, 2016). "We show for the first time that switching mice from a HF to standard diet improves several factors associated with the MetS, hippocampal insulin signaling alterations, and cognitive deficits." (PMID 27676071, 2016). "All these supported the cognitive impairments in APN-deficient mice were associated with cerebral insulin resistance, AD-like brain pathologies and mimicked the phenotypes of AD patients and rodent models." (PMID 27884163, 2016). "Leptin-deficient mice, a T2DM model, displayed impaired cerebral insulin signaling and cognitive impairments after treating with high-fat-diet." (PMID 27884163, 2016).
Cognitive impairment (continued). "Factors associated with RAIp included using ≤2 OADs; cognitive impairment, basal insulin use during follow-up; and higher RAI out-of-pocket costs ($36 to <$56 versus $0 to $6.30)." (PMID 27761472, 2016). "Many patients augmented their RAI plus OAD regimen with basal insulin, and this, together with cognitive impairment, was associated with persistence of RAI." (PMID 27761472, 2016). "Inter-relationships between plasma insulin concentration, insulin resistance, and the quality of glycemic control further complicate attempts to evaluate associations of any of these risk factors with cognitive impairment." (PMID 26060511, 2015). "It is also known that there is a higher risk for cognitive impairment when insulin regulation is disrupted." (PMID 25423262, 2014). "This statement can be stressed because cognitive deficits are associated with insulin signaling abnormalities." (PMID 25346723, 2014). "In conclusion, the present study shows that CCH induced by UCCAO decreased the protein O-GlcNAcylation, increased tau phosphorylation, dysregulated synaptic proteins and brain insulin signaling, and caused mild cognitive impairment." (PMID 24575038, 2014). "HFD feeding is linked to cognitive impairment mediated by brain insulin resistance and accelerated Aβ generation." (PMID 25152713, 2014). "Another study demonstrated that intranasal insulin treatment for 1 year appeared to improve the developmental delay in children suffering from 22q13 deletion syndrome that is associated with cognitive impairments, generalized hypotonia and autistic behavior." (PMID 23135822, 2013). "We demonstrated that insulin-deficient diabetes in APP/PS1 transgenic mice exacerbated cognitive deficits, characterized by excessive Aβ accumulation and subsequent formation of senile plaques." (PMID 21044348, 2010). "Insulin therapy was avoided due to cognitive impairment and a high risk of dosing errors." (PMID 42226859, 2026). "Changes in placental lipid metabolism and insulin signaling have been implicated in fetal programming of metabolic and neurodevelopmental disorders, which may contribute to cognitive impairments in offspring." (PMID 40290018, 2025). "Cognitive deficits are linked to insulin signaling abnormalities." (PMID 40283962, 2025). "Age-related deterioration in insulin sensitivity, elevated oxidative stress, and compromised mitochondrial function collectively increase susceptibility to cognitive impairment in older populations, potentially making older adults more responsive to the protective mechanism of SGLT2is." (PMID 41234238, 2025). "Upregulation of MEG3, by regulating insulin signaling in the brain, may offer neuroprotective effects and potentially alleviate cognitive impairment and neuronal damage associated with AD pathogenesis." (PMID 40869265, 2025). "Research suggests that cognitive impairment in schizophrenia may be linked to brain glucose and insulin resistance, indicating that brain insulin resistance could play a role in memory deficits in these patients." (PMID 41446289, 2025). "Moreover, studies in animal models have reported cognitive impairments linked to high-dose insulin exposure, which is consistent with the astrocyte dysfunction observed in C6 cells treated with high insulin levels." (PMID 40016145, 2025). "An increase in GLUT4 could be a response to enhance cognitive functions or counteract post-receptor insulin signaling and associated cognitive impairments in PNS states." (PMID 39000130, 2024). "Our findings support the evidence indicating that neuroinflammation in the hypothalamus and impairment in insulin resistance regulation may pose a risk for cognitive impairment after SAH." (PMID 39061961, 2024). "As insulin emerges as a potential therapeutic target, future investigations should aim to unravel the detailed cellular and molecular pathways, paving the way for innovative treatments for neuroinflammation‐associated cognitive disorders." (PMID 39073013, 2024).
Cognitive impairment (continued). "In addition, it decreased insulin signaling impairment in the brain, and attenuated glial activation related neuroinflammation and cognitive deficits associated with HFHS diet." (PMID 39897964, 2024). "We hypothesize that the ZnT3 deficiency and reduced brain zinc levels may cause cognitive impairment by negatively affecting glycose metabolism via decreased expression of key components of insulin signaling, as well as via changes in synaptic plasticity." (PMID 38807922, 2024). "Another study also supported this concept and found that impairment of acetylcholine synthesis is due to dysregulation of insulin secretion, whereas enhanced insulin levels reverse memory loss and cognitive impairment and are associated with elevated acetylcholine concentration in the brain." (PMID 36984824, 2023). "In conclusion, impaired insulin signaling in the brain is deleterious in causing early synaptosomal oxidative damage and synaptic loss that exacerbates with time and correlates with cognitive impairments." (PMID 38260013, 2023). "Current theories and hypotheses suggest that defective insulin signal transduction in the brain causes synaptic dysfunction and cognitive impairment in AD." (PMID 36923118, 2023). "Aging is associated with impaired neuromuscular junction function, ectopic fat deposition and low-grade inflammation, causing mitochondrial dysfunction, insulin resistance, dysfunctional adipokine and myokine release, causing sarcopenia and cognitive impairment." (PMID 37371414, 2023). "Interestingly, in the central nervous system, insulin is involved in the intersection of metabolic and cognitive disorders, and there is a suggested association between T2DM and SZ in drug‐naïve patients." (PMID 37515308, 2023). "In search of interventions targeting brain dysfunction and underlying cognitive impairment in schizophrenia, we look at the brain and beyond to the potential role of dysfunctional systemic metabolism on neural network instability and insulin resistance in serious mental illness." (PMID 36483840, 2022). "Indeed, data suggest individuals exhibiting cognitive deficits in aging maintain altered concentrations of exosomal proteins implicated in insulin signaling, lysosomal degradation/autophagy as well as synaptic integrity." (PMID 35299946, 2022). "There is substantial evidence supporting 4 pathophysiological mechanisms that may underlie the association between low muscle mass and cognitive impairment, that is, systemic inflammation, insulin, protein metabolism, and mitochondrial function." (PMID 35661882, 2022). "Inhibition of brain insulin signaling is thought to play a major role in the pathogenesis of neurodegenerative disorders and in sepsis, and to be a leading mechanism underlying cognitive impairment." (PMID 36527099, 2022). "Insulin and leptin play pivotal roles in the regulation of immunometabolism in the CNS and periphery, and dysfunction of these signaling pathways are associated with cognitive impairment." (PMID 34795562, 2021). "Furthermore, hyperphosphorylation of Tau protein in the hippocampus of central insulin-resistant rats has been linked to cognitive impairment." (PMID 34671194, 2021). "Moreover, intranasal insulin prevented anesthesia-induced apoptosis of hippocampal cells, which is thought to underlie cognitive impairment." (PMID 34326413, 2021). "Indeed, not only is a deficiency in CNS insulin action associated with cognitive impairments, but these risk factors are associated with an impaired cognitive response to insulin delivered therapeutically to the CNS by the intranasal route." (PMID 34545146, 2021). "The main limitations of the narrative review consist of the limited clinical evidence in the current literature of the causative role of anesthesia exposure in cognitive impairment >6 months postoperatively and the role of intranasal insulin administration in preventing the onset of DNR/pNCD." (PMID 33799976, 2021).
Cognitive impairment (continued). "Likewise, the presence of MS-related disorders also plays a role in the pathophysiology of neurological disorders, reflecting the association between deficiencies in secretion and action of insulin and mild cognitive impairment (MCI)." (PMID 34208833, 2021). "It is known that a reduction in insulin signaling is associated with cognitive impairment." (PMID 32188008, 2020). "High concentrations of GCs enhance the risk of developing T2DM by increasing hepatic glucose production and reducing insulin secretion and sensitivity, while also increasing the risk of cognitive impairment through hippocampal neuronal loss, decreased neurogenesis, and dendritic atrophy." (PMID 33221746, 2020). "However, impaired functions of IGF1 (insulin/insulin-like growth factor) signaling, which includes insulin receptor substrates, have been recognized as a risk factor for dementia and cognitive impairment." (PMID 32050523, 2020). "Recurrent or chronic hypoglycemia caused by insulin treatment may also contribute to permanent cognitive impairment." (PMID 32629878, 2020). "Given this background, we hypothesized that p66Shc deficiency might preserve the insulin sensitivity in maternal tissues and counteract the intergenerational transmission of cognitive impairment." (PMID 31641124, 2019). "Previous studies, in humans and in mice, point in the direction that some of the cognitive deficits of the old are due, among other causes, to the decreased levels or activity of insulin and IGF‐1 receptors and to a reduction in the signaling pathway by PI3K/Akt." (PMID 30884121, 2019). "These cognitive deficits are likely to be associated with impaired insulin signaling." (PMID 29572520, 2018). "Taken together, these observations support the hypothesis that AD (and cognitive impairment) may be associated with disrupted insulin signaling in the brain." (PMID 29945658, 2018). "All the findings pertaining to brain mitochondria suggested that brain mitochondrial dysfunction or an imbalance in mitochondrial dynamics in the brain would be the underlying mechanisms responsible for cognitive impairment associated with the obese- insulin resistant condition." (PMID 30233495, 2018). "Peroxisome proliferator-activated receptor γ (PPAR-γ), a nuclear receptor subfamily, that causes insulin sensitization and enhances glucose metabolism may be implicated in cognitive impairment in GDM." (PMID 30563117, 2018). "As reduced insulin signaling is associated with cognitive impairment and AD, adiponectin may influence cognition via reductions in insulin resistance." (PMID 30150999, 2018). "Exercise induces insulin sensitivity and glucose disposal through several pathways, including improvements in inflammation and oxidative stress that are high-risk factors for cognitive impairment and accelerated aging." (PMID 29156608, 2017). "As with insulin, leptin resistance is also associated withimpaired cognition, especially during aging, and impaired leptin function maycontribute to cognitive impairment in MCI in humans." (PMID 29072515, 2017). "Our results showed that intranasal insulin could improve cognitive deficits in ICV-STZ rats, which may be associated with reduced tau hyperphosphorylation, ameliorated activation of microglia and increased neurogenesis." (PMID 28382978, 2017). "Subsequent rodent studies indicate IER is equivalent or superior to CER in terms of weight loss, improving insulin sensitivity, preventing tumours, increasing resistance to neuronal damage, reducing cognitive impairment, protecting the heart and increasing the lifespan of rodents." (PMID 27233359, 2016). "More recently, findings from Suzanne Crafts group have shown that CSF insulin levels are reduced in early stages of AD or in the mild cognitively impairment and diets rich in fats and sugar lower CSF insulin levels in healthy adults and this was associated with reductions in cognitive functioning." (PMID 26693205, 2015).
Cognitive impairment (continued). "Loss of this insulin-mediated mechanism for matching glucose uptake to neuronal demand may explain the observed cognitive deficits in tasks of memory, attention, and speed, which all require intense neuronal activity." (PMID 23533158, 2013). "Saturated and trans fats, and fasting insulin, may already be associated with cognitive deficits in younger women." (PMID 24376410, 2013). "Additional evidence suggests that these effects are genotype dependent, such that groups with different genetic risk profiles for cognitive impairment or AD may show different dose-response curves following intranasal insulin administration." (PMID 23135822, 2013). "In that case, insulin resistance and low insulin levels in the CNS (interestingly referred as “diabetes of the brain”) would lead to the accumulation of beta-amyloid (the pathologic hallmark of AD) and cognitive impairment." (PMID 21070531, 2010). "However, despite increasing evidence that links insulin resistance to cognitive impairment, the precise mechanisms that underly T3D remain largely unknown." (PMID 41294899, 2025). "In addition, the deficiency of central insulin may reduce cerebral blood flow and blood supply to the cerebral cortex, which can also result in cognitive impairment." (PMID 39062768, 2024). "Finally, a decrease in molecules and pathways linked to insulin signaling was observed in both the hippocampal region and the cortex, which correlated with the reduction in dendritic spine density in hippocampal neurons and cognitive deficites." (PMID 38807922, 2024). "Therefore, altered insulin transport across the blood brain barrier as well as altered insulin receptor expression may explained the increased risk of developing cognitive impairment in patients suffering from primary headaches." (PMID 37721571, 2024). "Due to the significant neuromodulatory, protective and nutritional effects of insulin on the brain, insulin resistance in the brain might exacerbate Aβ deposition, tau hyperphosphorylation, and vascular inflammation, causing cognitive impairments in AD and VaD." (PMID 37214403, 2023). "Therefore, deregulation of insulin-dependent glucose transport in the brain may be a cause of cognitive impairment." (PMID 34576151, 2021). "In addition, a reduction in insulin signaling is known to be associated with cognitive impairment." (PMID 32188008, 2020). "Our present data implied the importance of HOMA-IR measurement in elderly cancer patients, because those with high HOMA-IR scores may be at a high risk for developing cognitive impairment and may benefit from early treatment, such as the use of biguanide, to reduce insulin sensitivity." (PMID 31661025, 2019). "Whether insulin administration can attenuate cognitive impairments associated with age-related inflammation warrants further investigation, perhaps using more direct methods of administration in a natural model, to closer represent the underlying physiological mechanisms." (PMID 30619085, 2018). "Reductions in brain insulin signaling due to insulin deficiency or insulin receptor resistance could account for the majority of molecular, biochemical, and histopathological lesions, as well as cognitive impairment in AD." (PMID 27525190, 2016). "Besides, epidemiological studies have shown that both type 1 and type 2 diabetic patients have cognitive impairment and an increased risk of AD, mainly in older patients, and also that insulin administered to AD patients to keep glycemic levels constant can improve memory formation." (PMID 25346723, 2014). "The patient was discharged on a basal-bolus insulin therapy managed by his parents due to his cognitive impairment." (PMID 39996062, 2025). "Here, we analyse the potential mechanisms of irisin in improving cognitive impairment, focusing on energy metabolism, insulin resistance, Aβ deposition, oxidative stress and inflammation, synaptogenesis and plasticity." (PMID 40660735, 2025).